LIPA (lipase A, lysosomal acid type)
Diseases named in the same sentence as LIPA in open-access papers (continued):
Sharing a sentence is not in itself a finding about the gene and the disease.
X-linked adrenoleukodystrophy (2 papers, 2020 to 2021). X-linked adrenoleukodystrophy (X-ALD) is a peroxisomal disorder resulting in cerebral demyelination, axonal dysfunction in the spinal cord leading to spastic paraplegia, adrenal insufficiency and in some cases testicular insufficiency.
acute pancreatitis (1 paper, 2022). An acute inflammatory process that leads to necrosis of the pancreatic parenchyma. "The core index results of acute pancreatitis in each group of rats confirmed that HLAP raised the serum AMLY and LIPA levels to 3 times higher than normal levels." (PMID 35566136, 2022).
autoimmune polyendocrinopathy (1 paper, 2021). A group of diverse conditions that are characterized by spontaneous, multi-organ autoimmunity, which target both endocrine (adrenal, gonad, pancreatic islet cells, parathyroid, pituitary, thyroid) and non-endocrine (gastrointestinal, integumentary, lymphatic) tissues. "For 3 of the variants (AIRE:c.254A>G [autoimmune polyendocrinopathy], LIPA:c.260G>T [Wolman’s disease], and GNE:c.2228T>C [inclusion body myopathy (HIBM)]), carrier frequency was assayed previously in Mizrahi Jews and found to be similar to the frequencies reported here." (PMID 34288589, 2021).
bacteremia (1 paper, 2017). "Because LipA is a lipase that breaks down long-chain fatty acids, lipA, gspD, and gspE mutant strains are incapable of growing on long-chain fatty acids as a sole carbon source and are defective in in vivo growth in a neutropenic murine model of bacteremia." (PMID 28348979, 2017).
clear cell carcinoma (1 paper, 2024). "We further validated the increased expression of LIPA in OCa using IHC with the LIPA antibody by employing a tissue microarray (TMA) consisting of 21 serous, 44 mucinous, 22 endometrioid adenocarcinoma, 3 clear cell carcinoma tumors and 5 normal/benign ovarian tissues." (PMID 38339252, 2024).
colorectal tumors (1 paper, 2024). "Another two macrophage clusters with a lipid-associated (LA) metabolism transcriptional signature, including genes such as FABP5, LPL, and LIPA, named RTM_LA (n = 3569) and Mac_LA (n = 1249), were found enriched in breast, lung, and colorectal tumors." (PMID 38972873, 2024).
cystic fibrosis (1 paper, 2011). Autosomal recessive disorder caused by pathogenic variants in the CFTR gene (cystic fibrosis transmembrane conductance regulator), which encodes a chloride and bicarbonate channel expressed in epithelial cells, and follow the diagnosis criteria. "This type of transporter associated with expression of extracellular lipases or phospholipases (like LipA or PlcB) could allow P. aeruginosa to degrade phosphatydylethanolamine or phosphatydylcholine as one nutrient source, for example in the lungs of cystic fibrosis patients." (PMID 22046254, 2011).
glaucoma (1 paper, 2016). Increased pressure in the eyeball due to obstruction of the outflow of aqueous humor. "Two variants (p.A10S in TRMU and.G185S in ACADS) also appear in HGMD, and are flagged as “clinically associated” in dbSNP, p.R76K in MYOC was believed to contribute to glaucoma in a di-genic inheritance and p.G5R in LIPA was shown in a functional assay to cause reduced enzymatic activity." (PMID 27175728, 2016).
Granuloma (1 paper, 2022). A compact, organized collection of mature mononuclear phagocytes, which may be but is not necessarily accompanied by accessory features such as necrosis. "When compared to granuloma periphery or mucosa, CD68+ cells in the granulomata demonstrated increased gene expression in lysosome or macrophage-related genes such as CTSD, CD68, HEXB, ATP6V0A1, CTSK, LIPA, CD63." (PMID 36302964, 2022).
heart failure (1 paper, 2018). Inability of the heart to pump blood at an adequate rate to meet tissue metabolic requirements. "Additionally, the ACTA2 gene is located 220 kb away from the heart failure GWAS locus proximal to the CH25H and LIPA genes on chromosome 10q21." (PMID 29988018, 2018).
Insulin resistance (1 paper, 2012). Increased resistance towards insulin, that is, diminished effectiveness of insulin in reducing blood glucose levels. "We tested the hypothesis that TAG accumulation in the liver induced by short-term high-fat diet (HFD) in rats leads to the dysregulation of endogenous TAG degradation by lysosomal lipase (LIPA) via lysosomal pathway and is causally linked with the onset of hepatic insulin resistance." (PMID 21904679, 2012).
lymphocytic leukemias (1 paper, 2016). "In lymphocytic leukemias, metabolic enzymes related with lipid biosynthesis, such as lipase A (LIPA) and pyruvate dehydrogenase lipoamide kinase isozyme 1 (PDK1), are targets of miR-125b." (PMID 27551267, 2016).
ovarian carcinoma (1 paper, 2025). A malignant neoplasm originating from the surface ovarian epithelium. "This novel LIPA-targeted therapy has been demonstrated as potentially effective also for ovarian cancer, where LIPA is up-regulated, as well as in renal carcinoma." (PMID 39858538, 2025).
ovarian tumors (1 paper, 2024). "The results indicated that the expression of LIPA is increased in all subtypes of ovarian tumors in comparison to normal/benign ovarian tissue." (PMID 38339252, 2024). "The findings indicate that LIPA has a significantly elevated expression level in ovarian tumors when compared to normal tissues." (PMID 38339252, 2024).
pulmonary TB (1 paper, 2023). "Interestingly, the rs1051338 and rs7922269 single-nucleotide polymorphisms of LIPA are associated with individual susceptibility to pulmonary TB." (PMID 38022579, 2023).
renal cell carcinoma (1 paper, 2023). "The results showed that FUCA1 was down-regulated and SLC40A1, VSIG4, CRYBB1 and LIPA were up-regulated in renal cell carcinoma and 786-O, and the difference was statistically significant." (PMID 37361571, 2023).
retinal degeneration (1 paper, 2023). Degeneration of the retina. "Homologs of two genes causing cholesterol storage disorders, Npc1a / NPC1 and Lip4 / LIPA, were independently confirmed as loss-of-function enhancers of αSyn-induced retinal degeneration." (PMID 37200393, 2023).
sarcoma (1 paper, 2023). A usually aggressive malignant neoplasm of the soft tissue or bone. "Its expression was detected together with APOE, APOC1 (apolipoprotein C1), FABP5 (fatty acid binding protein) and LIPA (Lipase A), genes involved in lipid transport and metabolism and highly detected in breast, sarcoma, colon, lung and other cancers." (PMID 37342322, 2023).
Sepsis (1 paper, 2025). Sepsis is defined as life-threatening organ dysfunction caused by a dysregulated host response to infection. "Moreover, it was found that the expression of lytA in a sepsis model was inhibited in the D39 lipA+ strain, but not in the ΔlipA mutant and that the induction of lipA expression results in the inhibition of autolysis." (PMID 40284663, 2025).
visceral leishmaniasis (1 paper, 2015). A severe form of leishmaniasis characterized by irregular bouts of fever, substantial weight loss, swelling of the spleen and liver, and anemia (which may be serious). "infantum chagasi proteinantigen (LiPA) IgGs purified from the sera of dogs with visceral leishmaniasis." (PMID 25710003, 2015). "Phage clones reactive with anti-LiPA IgGs were also tested for reactivity with IgGs purified from the sera of dogs experimentally infected with T. cruzi, because of the known cross reaction between visceral leishmaniasis antibodies and Chagas' disease antibodies in dogs." (PMID 25710003, 2015).
tumor (38 papers, 2015 to 2026). "Exosomes released by melanoma cells were shown to contribute to the induction of a tumor-promoting phenotype of Tumor Associated Macrophages (TAM) via exosomal miR-125b-5p targeting the lysosomal acid lipase A (LIPA)." (PMID 36674479, 2023). "A gene fusion involving PTEN and LIPA(LIPA-PTEN) leading to removal of the sequence encoding the PTEN Tensin C2 domain was identified in a patient tumor." (PMID 32839463, 2020). "Expression analysis using the TNMplot web tool, TCGA data sets, and immunohistochemistry analysis using a tumor tissue array showed that LIPA is highly expressed in OCa tissues, compared to normal tissues." (PMID 38339252, 2024). "Using tumor tissue array data, along with TCGA data, we demonstrated that LIPA is highly expressed in all four subtypes of OCa." (PMID 38339252, 2024). "Through the analysis of public databases and tumor tissue arrays, we found an elevated expression of LIPA in OCa tissues." (PMID 38339252, 2024). "Raj and colleagues show that ERX-41 inhibits lipase-independent functions of LIPA and induces ER stress in different tumor types, providing a therapeutic strategy in PDX models of pancreas, ovarian and triple-negative breast cancer." (PMID 35654861, 2022). "Results showed that the expression level of genes including MORF4L2, CTSL1, WIPF1, CXCL13, C5orf15, LIPA, and ISG20 significantly elevated in tumor tissues." (PMID 36639648, 2023). "Our data also showed that GZMB+-neutrophils have anti-tumor activity when activated by a TLR4 agonist unlike those devoid of GZMB, and their infiltration into tumor probably contributed to the LipA-mediated tumor cell death." (PMID 29983866, 2018).
cancer (23 papers, 2015 to 2026). A tumor composed of atypical neoplastic, often pleomorphic cells that invade other tissues. "We recently developed ERX-41, a small molecule that exacerbates ER stress in cancer cells by inhibiting the endoplasmic reticulum-localized function of Lysosomal acid lipase A (LIPA)." (PMID 41897416, 2026). "Last but not least, LIPA expression was downregulated in multiple forms of human cancers by data mining of the TCGA database." (PMID 35917184, 2022).
infection (13 papers, 2016 to 2026). The state of being infected such as from the introduction of a foreign agent such as serum, vaccine, antigenic substance or organism. "The antimony-susceptibility, promastigote growth curves, infection rates and parasite loads in macrophages were studied in LIPA-WT, SbIIIR-0.5 and SbIIIR-5.5 mM parasites recovered from infected guts of Ph. papatasi." (PMID 38941845, 2024). "Early infection triggered a monocyte-specific antiviral response marked by changes in the expression of genes associated with lipid metabolism (LIPA, lysosomal acid lipase) and chemotaxis (CCR1 and CCR2)." (PMID 41332545, 2025). "Further, we found that the human ortholog, LAL/LIPA, rescues lipl-1-associated immune defects and improves survival upon infection suggesting potential evolutionary conservation of these molecular functions." (PMID 41385585, 2025). "LIPA inhibition increased EBV titers during primary infection, demonstrating a functional antiviral role." (PMID 41332545, 2025). "vesicatoria (Xcv), LipA is expressed from an early stage of tomato leaf infection and is required for wild-type virulence." (PMID 26753904, 2016). "However, the infection rate of SbIIIR-5.5 mM parasites remained significantly lower than in LIPA-WT and SbIIIR-0.5 mM lines." (PMID 38941845, 2024). "We reasoned that if S. aureus were to be introduced into similar lipoic acid-limiting environments in vivo (nearly all lipoic acid is protein bound, while free lipoic acid has a very short half-life), then survival of the bacterium during infection would necessarily require LipA." (PMID 27701474, 2016). "We have thus far determined that LipA, LipM, and LipL comprise components of the de novo lipoic acid biosynthesis pathway and LplA1 and LplA2 constitute enzymes involved in lipoic acid salvage with LplA2 exerting its most notable activity during infection." (PMID 27701474, 2016). "Lastly, we show that human hLAL/LIPA rescues lipl-1 lof-associated immune defects and enhances worm survival upon PA14 infection but does not compensate for fertility phenotypes." (PMID 41385585, 2025). "The importance of the genes lipA (from PAI 1) and copR (from PAI 2) for bacterial invasion and replication indicates that they are required for full invasiveness of B. cenocepacia and may function as virulence determinants for bacterial pathogenesis and host infection." (PMID 28347342, 2017).
genetic disease (7 papers, 2017 to 2025). "Cholesterol ester storage disease (CESD) is an autosomal recessive genetic disease caused by the mutation of the LIPA gene encoding lysosomal acid lipases (LAL)." (PMID 28662670, 2017). "Finally, mutations of LIPA gene cause lysosomal acid lipase (LAL) deficiency, a severe genetic disorder, are associated with accumulation of cholesteryl esters and triglycerides in hepatocytes." (PMID 31375010, 2019).
cardiovascular disease (5 papers, 2016 to 2024). "We discuss below associations of cardiovascular disease risk with more common LIPA variants and functional correlates; note that these differ from known disease-causing mutations in LIPA." (PMID 36204319, 2022). "Other examples include artery eQTL for the cardiovascular diseases associated gene PHACTR1 (P = 8 × 10−10); the lysosomal acid lipase (LIPA) gene and microglia eQTL (P = 2 × 10−11); and the ABO blood group gene with plasma pQTL (P = 1 × 10−21)." (PMID 39563277, 2024).
bacterial infection (2 papers, 2022 to 2026). "The lipase LipA from Pseudomonas aeruginosa is an extracellular enzyme that plays an important role in bacterial infections." (PMID 42320633, 2026).
LIPA also shares sentences with these, for which no sentence is quoted: Hepatic steatosis (11 papers); Cirrhosis (8); liver fibrosis (6); Gaucher disease (5); liver disease (5); diabetes (4); hypertriglyceridemia (4); liver cancer (4); Splenomegaly (4); Hepatosplenomegaly (3); hypoalphalipoproteinemia (3); lipodystrophy (3); liver failure (3); Metabolic disorders (3); Niemann-Pick disease (3); prostate carcinoma (3); anemia (2); cirrhosis of the liver (2); Clear Cell Renal Cell Carcinoma (2); dyslipidaemia (2); emphysema (2); Fabry disease (2); Failure to thrive (2); glioblastoma (2); hepatocellular carcinoma (2); liver dysfunction (2); Niemann-Pick disease type C (2); psychosis (2); Smith-Lemli-Opitz syndrome (2); Adrenal insufficiency (1).
A further 77 diseases each share a sentence with LIPA in 1 paper.